LMTK3 (lemur tyrosine kinase 3)
Description:
Protein kinase which phosphorylates ESR1 (in vitro) and protects it against proteasomal degradation. May also regulate ESR1 levels indirectly via a PKC-AKT-FOXO3 pathway where it decreases the activity of PKC and the phosphorylation of AKT, thereby increasing binding of transcriptional activator FOXO3 to the ESR1 promoter and increasing ESR1 transcription. Involved in endocytic trafficking of N-methyl-D-aspartate receptors (NMDAR) in neurons (By similarity).
Synonyms: KIAA1883; TYKLM3; LMR3; AATYK3; PPP1R101
Tractability: Small molecule: a high-quality ligand is known; it belongs to a druggable protein family. Antibody: UniProt predicts a signal peptide or a membrane-spanning region. PROTAC: its protein half-life has been measured; a small molecule that binds it is known.
Target class: Enzyme; Transferase
Gene: Protein-coding gene on chromosome 19 (48,485,271 to 48,513,935, reverse strand). Ensembl gene ENSG00000142235.
Subcellular location: Membrane; Cell projection, axon; Cell projection, dendrite; Golgi apparatus membrane
Subcellular location (Human Protein Atlas): Nucleoplasm; Cell Junctions
Gene Ontology:
Molecular function: protein binding; protein serine kinase activity; protein kinase activity; ATP binding; protein serine/threonine kinase activity
Cellular component: axon; cytoplasm; dendrite; endomembrane system; Golgi membrane; membrane
Genetic constraint (gnomAD): Loss-of-function variants: 27 observed, 72.04 expected, observed/expected ratio (o/e) 0.37, 90% interval 0.28 to 0.52. The synonymous counts are far from expectation, so gnomAD's model fits this gene poorly and the ratio says little. Missense variants: 1,655 observed, 1,532 expected, observed/expected ratio (o/e) 1.08, 90% interval 1.04 to 1.12. Synonymous variants: 912 observed, 719.71 expected, observed/expected ratio (o/e) 1.27, 90% interval 1.2 to 1.34.
Homologues: Orthologues: macaque LMTK3 (99% identical), chimpanzee LMTK3 (98% identical), dog LMTK3 (95% identical), pig LMTK3 (94% identical), guinea pig LMTK3 (88% identical), rat Lmtk3 (88% identical), mouse Lmtk3 (88% identical), tropical clawed frog lmtk3 (42% identical), zebrafish lmtk3 (34% identical). Paralogues in human: AATK (29% identical).
Diseases named in the same sentence as LMTK3 in open-access papers:
LMTK3 is named in the same sentence as 30 diseases in open-access papers, as found by Europe PMC text mining. Sharing a sentence is not in itself a finding about the gene and the disease. The quoted sentences say what the papers report.
breast carcinoma (19 papers, 2015 to 2026). "The lemur tyrosine kinase-3 (LMTK3) receptor has been linked to estrogen responsiveness in breast cancer." (PMID 38638686, 2024). "LMTK3 is significantly elevated in high-grade breast tumors and is associated with poor survival rates in different breast cancer cohorts." (PMID 30944027, 2019). "MIR2052HG associated with EGR1 and facilitated its binding to the LMTK3 gene promoter to activate LMTK3 expression, which in turn, promoted ERα-positive breast cancer cell growth." (PMID 30944027, 2019). "We and others have demonstrated that LMTK3 expression is significantly elevated in high-grade breast tumors and is associated with poor survival rates in different breast cancer cohorts." (PMID 29540829, 2018). "Based on previous observations associating LMTK3 with tamoxifen resistance in breast cancer, we set out to investigate a possible role of LMTK3 in breast cancer cells’ response to cytotoxic treatment in vitro and in vivo." (PMID 29540829, 2018). "HSP27 has been previously implicated in breast cancer progression and therapy resistance; therefore, the phosphorylation at Ser15 and Ser82 by LMTK3 may indicate an important pathway that requires further elucidation." (PMID 34582708, 2021). "LMTK3 has been implicated in both de novo and acquired endocrine resistance in breast cancer." (PMID 30944027, 2019). "In fact, we could confirm that LMTK3, encoding for Lemur Tyrosine Kinase 3 known to promote invasion in breast cancer, was widely overexpressed in both Cs and Ps of LT and ST patients." (PMID 26188123, 2015). "Moreover, given the unusual predisposition of humans to ER+ breast cancer, the positive selection of LMTK3 indicates that it could be a key driver of this cancer subtype in humans." (PMID 34582708, 2021). "In breast cancer cells, LMTK3 regulates ERa via phosphorylation activity and is directly implicated in the modulation of endocrine resistance." (PMID 38638686, 2024). "The amount of LMTK3 is overexpressed in aggressive breast cancer and closely correlates with survival and responsiveness to hormonal therapy." (PMID 38638686, 2024). "Breast cancer therapy research remains tricky due to a paucity of structural investigations on LMTK3." (PMID 38638686, 2024). "In several breast cancer cohorts, LMTK3 expression is markedly higher in high-grade breast tumors and is linked with poor survival rates." (PMID 38638686, 2024). "ERa is highly expressed in breast cancer, and LMTK3 phosphorylation of ERa promotes breast cancer cell proliferation, angiogenesis, migration, and progression." (PMID 38638686, 2024). "Additional C36 analogues are also being synthesized to improve the binding affinity of the drug to LMTK3 and to increase its inhibitory properties against LMTK3 activity both in vitro (kinetic analysis) and in breast cancer cell lines." (PMID 36614307, 2023). "Treatment of different breast cancer cell lines with C36 led to decreased proliferation and increased apoptosis, further reinforcing the prospective value of LMTK3 inhibitors for cancer therapy." (PMID 36614307, 2023). "Ultimately, this paper provides a steppingstone for the development and optimization of oral LMTK3 inhibitors, including C36, for use in clinical applications, either as a monotherapy or as a combination therapy in breast cancer." (PMID 36614307, 2023). "LMTK3 was originally identified as an important regulator of estrogen receptor alpha (ERα) activity in breast cancer (BC) following a whole human kinome siRNA screen." (PMID 36614307, 2023). "It plays a cancer-promoting role in breast cancer, and C28, a LMTK3 small-molecule inhibitor, can promote proteasome-mediated LMTK3 degradation." (PMID 35590394, 2022). "Mechanistically, through a whole-genome microarray analysis, it was demonstrated that LMTK3 silencing affects the expression of a number of genes related to breast cancer progression and importantly, a subset of genes involved in tamoxifen resistance." (PMID 34582708, 2021).
breast carcinoma (continued). "In the last decade, LMTK3 (lemur tyrosine kinase 3) has emerged as an important player in breast cancer, contributing to the advancement of disease and the acquisition of resistance to therapy through a strikingly complex set of mechanisms." (PMID 34582708, 2021). "While initially identified to have a role in ERα (oestrogen receptor alpha) regulation in breast cancer, LMTK3 is now known to fuel tumourigenesis through many diverse mechanisms." (PMID 34582708, 2021). "Depletion of LMTK3 was shown to enhance the sensitivity of both prostate and breast cancer cells to an IGF1R inhibitor as demonstrated by a reduction in viability when exposed to an IGF1R tyrosine kinase inhibitor." (PMID 34582708, 2021). "Ectopic expression of miR-34a and miR-182 in LMTK3-overexpressing breast cancer cell lines inhibited cell proliferation through directly binding to the 3’UTR of LMTK3 mRNA and consequently inhibiting both its stability and translation." (PMID 34745935, 2021). "Clinical analyses also revealed the importance of LMTK3 as a predictive and prognostic marker in breast cancer." (PMID 34582708, 2021). "LMTK3 promotes breast cancer progression and decreased the sensitivity to doxorubicin treatment by decreased activity of ataxia‐telangiectasia mutated kinase." (PMID 32865871, 2020). "The results showed higher LMTK3 expression was correlated with progression and poor prognosis in breast cancer." (PMID 32865871, 2020). "Then they used breast cancer cases to explore the relationship of clinical pathological features and LMTK3." (PMID 32865871, 2020). "MIR2052HG depletion in breast cancer cells results in a decrease in LMTK3 expression and cell growth." (PMID 30944027, 2019). "To further define the relationship between MIR2052HG and LMTK3, we transfected LMTK3 overexpressing constructs into ERα-positive breast cancer cells with MIR2052HG-knockdown, followed by cell growth and colony forming assays." (PMID 30944027, 2019). "Recently, LMTK3, a serine-threonine-tyrosine kinase, has gained attention in breast cancer with respect to its roles in pathogenesis and therapy resistance of breast cancer." (PMID 30944027, 2019). "Using 2D monolayers as well as 3D-spheroids cultures we show that breast cancer cells stably overexpressing LMTK3 are more resistant to doxorubicin treatment when compared to the parental ones." (PMID 29540829, 2018). "In this study, we implicate LMTK3 in the protection of breast cancer cells from DNA DSBs as induced by doxorubicin." (PMID 29540829, 2018). "Taken together, these data indicate that breast cancer cells overexpressing LMTK3 are less sensitive (or more resistant) to doxorubicin treatment, compared to their respective parental cell lines expressing basal levels of LMTK3." (PMID 29540829, 2018). "In aggregate, our findings show for the first time a contribution of LMTK3 in cytotoxic drug resistance in breast cancer." (PMID 29540829, 2018). "As anticipated, LMTK3 overexpression increased tumor growth, as previously observed in an in vivo study using T47D and T47D/LMTK3 breast cancer cell lines further supporting its oncogenic role." (PMID 29540829, 2018). "Lastly, we examined the expression levels of LMTK3 in 148 breast cancer patients from 4 individual studies, pre and post-chemotherapy treatment." (PMID 29540829, 2018). "In summary, our data illustrate a novel role and involvement of LMTK3 in doxorubicin resistance in breast cancer." (PMID 29540829, 2018). "Using both 2D and 3D tissue culture models, we found that overexpression of LMTK3 decreased the sensitivity of breast cancer cell lines to cytotoxic (doxorubicin) treatment." (PMID 29540829, 2018). "We have recently shown that lemur receptor tyrosine kinase 3 (LMTK3) promotes invasion in breast cancer through GRB2-mediated induction of integrin family members, supporting our data presented here." (PMID 26089344, 2015).
breast carcinoma (continued). "DDX5 enables LMTK3 to facilitate the processing of pri-miRNAs (pri-miR-34a, pri-miR-182, and pri-miR-196-a2) for maturation, and upregulated miR-34a and miR-182 can target and inhibit LMTK3 expression, consequently suppressing the oncogenic effects of LMTK3 in breast cancer." (PMID 38689093, 2024). "Additionally, miR-34a suppresses the proliferation of breast cancer via specifically targeting LMTK3 and holds promise as an anti-ER (estrogen receptor) agent in breast cancer therapy." (PMID 38834687, 2024). "miR-34a is known to have a tumour suppressor role; however, this study further demonstrated that the oncogenic miRNA, miR-182, also has a tumour suppressor role in breast cancer cells overexpressing LMTK3, highlighting the complex signalling network surrounding LMTK3 regulation." (PMID 34582708, 2021). "In addition, LMTK3 (lemur tyrosine kinase 3), an important node in the network diagram, plays an important role in the progression of a variety of cancers (breast cancer, lung cancer, CRC, etc.)." (PMID 34938735, 2021). "In addition to conferring drug resistance and regulating ERα, LMTK3 also has roles in promoting invasiveness in breast cancer." (PMID 34582708, 2021). "Overcoming resistance would represent a great progress in breast cancer management and LMTK3 may be a valuable new target." (PMID 34582708, 2021). "Interestingly, LMTK3 also enhanced resistance to endocrine therapy in breast cancer by reducing autophagy and confers chemoresistance in breast cancer by the formation of γH2AX foci." (PMID 32865871, 2020). "The pathogenetic role of LMTK3 in breast cancer has been confirmed by several studies." (PMID 32865871, 2020). "d Correlations of LMTK3 expression with ESR1 in TCGA breast cancer patients." (PMID 30944027, 2019). "c Correlations of LMTK3 expression with ESR1 in 2509 METABRIC breast cancer patients." (PMID 30944027, 2019). "Consistent with this hypothesis, we found that knockdown of MIR2052HG using a pooled ASO in human ER-positive CAMA-1 breast cancer cells resulted in a dramatic decrease of LMTK3 expression." (PMID 30944027, 2019). "A prior study has shown that methylation is not a prevalent mechanism in the control of LMTK3 expression in breast cancer, and several somatic mutations in LMTK3 have been associated with overall survival." (PMID 30944027, 2019). "Importantly, we underpin these results by using a breast cancer xenograft mouse model revealing that increased LMTK3 levels decrease the antitumor activity of doxorubicin." (PMID 29540829, 2018). "Finally, in a clinical setting, after analysing pre- and post-chemotherapy samples from breast cancer patients, we detected a positive correlation between increased number of chemotherapy cycles and LMTK3 protein levels." (PMID 29540829, 2018). "Finally, we examined the expression of LMTK3 in 148 pairs of primary breast cancer cases, before and after receiving chemotherapy." (PMID 29540829, 2018). "Interestingly, breast cancer cells overexpressing LMTK3 delayed the generation of double strand breaks (DSBs) after exposure to doxorubicin, as measured by the formation of γH2AX foci." (PMID 29540829, 2018). "Together, these relationships emphasize the centrality of MAPK stress circuitry in shaping the molecular phenotype of the examined breast-cancer subtypes, while also highlighting the unique positioning of LMTK3 as a MAPK-associated but not directly interconnected component." (PMID 41465262, 2025). "In addition to LMTK3 inhibition, C28 was found to induce apoptosis and G2/M arrest in breast cancer cells, indicating that C28 may exert its anti-cancer effects through an additional mechanism." (PMID 34582708, 2021).
breast carcinoma (continued). "Overall, LMTK3, KAP1 and PP1α are co-expressed in the majority of breast cancers where they collaborate to repress tumour suppressor-like genes through the remodelling of chromatin, which promotes a more aggressive phenotype." (PMID 34582708, 2021). "LMTK3 knockdown strongly reduced the expression of TFF1 in the primary screen, in addition to GREB1 (growth regulation by oestrogen in breast cancer 1) and PGR (progesterone receptor) secondary screens." (PMID 34582708, 2021). "As a direct target of MIR2052HG, LMTK3 regulated downstream PKC/AKT/FOXO3 and PKC/MAPK/RSK1/ERα signaling, therefore regulating ERα-positive breast cancer growth and AI response." (PMID 30944027, 2019). "Since LMTK3 has been shown to have a fundamental role in breast cancer progression and since there are no current drugs available targeting this oncogenic kinase, LMTK3 inhibitors could represent a valid alternative treatment to breast cancer patients." (PMID 36614307, 2023). "In this study, we did find that LMTK3 knockdown could inhibit cell viability, enhance G1 cell cycle arrest, promote apoptosis, and reduce the mRNA and protein levels of ERα in both ERα-positive EEC Ishikawa and breast cancer MCF-7 cells." (PMID 34745935, 2021).
bladder cancer (3 papers, 2020 to 2025). "LMTK3 could be used as a diagnostic and prognostic biomarker in bladder cancer." (PMID 32865871, 2020). "Thus, targeting LMTK3 may hold potential as a diagnostic and prognostic biomarker and as a possible future treatment for bladder cancer." (PMID 32865871, 2020). "Lemur tyrosine kinase 3 (LMTK3) as a bladder cancer oncogene has been shown to promote bladder cancer cell proliferation and migration through ERK/MAPK pathway." (PMID 40183046, 2025). "In this study, we revealed that LMTK3 was overexpressed in bladder cancer and was positively correlated with malignancy of bladder cancer." (PMID 32865871, 2020). "We assessed phosphorylation of MEK and ERK1/2 in bladder cancer cells depleted of LMTK3 and demonstrated a reduced phosphorylation status compared with the control group." (PMID 32865871, 2020). "Mechanistically, LMTK3 promoted bladder cancer cell proliferation and progression by activating the ERK/MAPK pathway." (PMID 32865871, 2020). "In conclusion, we extend the status of LMTK3 as an oncogene in bladder cancer and provide evidence for its function via the activation of the ERK/MAPK pathway." (PMID 32865871, 2020). "Our study showed that LMTK3 was up‐regulated in bladder cancer compared with paracancerous tissue; then the clinic data analysis indicated that high LMTK3 expression status was associated with tumor grade and stage." (PMID 32865871, 2020). "LMTK3 was overexpressed in bladder cancer and this increased expression closely correlated with poor survival of bladder cancer patients." (PMID 32865871, 2020). "We found that the capability of bladder cancer cells proliferation and migration was decreased when the LMTK3 gene was knocked down." (PMID 32865871, 2020). "Our study showed the phosphorylation of MEK and ERK1/2 in the si‐LMTK3‐treated group was decreased compared with the si‐control group in bladder cancer cells." (PMID 32865871, 2020). "In conclusion, our research indicates for the first time that LMTK3 is an oncogene in bladder cancer." (PMID 32865871, 2020). "LMTK3 overexpression induced cell growth and migration whereas its depletion promoted apoptosis of bladder cancer cells." (PMID 32865871, 2020). "Knockdown of LMTK3 in bladder cancer cells triggered cell‐cycle arrest at G2/M phase, suppressed cell growth, and induced cell apoptosis in bladder cancer cells." (PMID 32865871, 2020). "In vitro, down‐regulation of LMTK3 inhibits bladder cancer cells proliferation and migration, and induces cell‐cycle arrest and apoptosis." (PMID 32865871, 2020). "In this study, we demonstrated that LMTK3 was overexpressed in bladder cancer and was positively correlated with bladder cancer malignancy." (PMID 32865871, 2020). "In addition, the molecular mechanisms of LMTK3 regulating the ERK/MAPK signaling pathway on the progression of bladder cancer should be elucidated." (PMID 32865871, 2020). "In this study, we found by WGCNA analysis that LMTK3 was a hub gene in bladder cancer." (PMID 32865871, 2020). "Then we used bladder cancer cells to explore the biological role of LMTK3." (PMID 32865871, 2020). "Hence we focused on MAPK/ERK signaling to further explore the potential molecular mechanism of LMTK3 in bladder cancer." (PMID 32865871, 2020). "Then we clarified the clinical significance and oncogenic role of LMTK3 in bladder cancer." (PMID 32865871, 2020). "Here, we characterise LMTK3 as an oncogene in bladder cancer." (PMID 32865871, 2020). "For instance, LMTK3 expression turned out to be a negative prognostic factor in patient with gastric cancer; its overexpression in bladder cancer was correlated with bladder cancer malignancy and predicted poor survival." (PMID 34064250, 2021). "However, the role of LMTK3 in bladder cancer has not been studied." (PMID 32865871, 2020).
breast tumors (3 papers, 2018 to 2024). "LMTK3 inhibition in breast tumors affected ERa at two levels: mRNA production and protein stability." (PMID 38638686, 2024). "Targeting LMTK3 in ERa-positive breast tumors is thought to be more successful than downregulating ERa mRNA expression in cancer cells." (PMID 38638686, 2024). "In human cancers, immunohistochemistry staining of LMTK3 in pre- and post-chemotherapy breast tumor pairs from four separate clinical cohorts revealed a significant increase of LMTK3 following both doxorubicin and docetaxel based chemotherapy." (PMID 29540829, 2018).